APP (amyloid beta precursor protein)
Diseases named in the same sentence as APP in open-access papers (continued):
Sharing a sentence is not in itself a finding about the gene and the disease.
neurological disorders (67 papers, 2005 to 2025). "In recent years, this multifunctionality has linked PLTs to a wide spectrum of systemic and neurological diseases, since they contain abundant α-synuclein, APP and β-amyloid, and share key molecular and signaling machinery with neurons." (PMID 41303651, 2025). "APP homeostasis is essential for proper neurological function with adequate expression, limiting inflammation, but an imbalance increases the risk of neurological disorders." (PMID 38674105, 2024). "Aβ represents peptide amino acids, the derivatives of the amyloid precursor proteins (APP), and their upregulation causes neurological disorders like AD." (PMID 36425574, 2022). "However, of the three only APP has been implicated in neurological disease." (PMID 26814888, 2016). "A focused examination of six AD-related genes – APOE, APP, BIN1, CLU, MAPT and PSEN1 – and SMARCA5, which has been linked to neurological disorders, revealed different expression patterns across cell types and AD." (PMID 41255979, 2025). "As in many neurological disease models, in APP/PS1 mice, the inhibitory interneurons of the hippocampus are affected before general neuronal loss occurs." (PMID 39200191, 2024). "Most BPA-perturbed proteins interact with hubs in the brain known to be involved in several neurological disorders, such as APP and ESR2." (PMID 37664457, 2023). "The nervous system disease class consists of proteins APP, DYNC1H1, DYNC1I2, HINT1, LSM2, RNF11, SNCA in between 30% and 40% association." (PMID 34918006, 2022). "Several of these such as NOTCH2, APP, ITM2B and PTGDS have been implicated in neurological disorders." (PMID 36185601, 2022). "In an effort to rigorously consider biological variables essential to neurological diseases, female APP mice were subjected to the same behavioral testing as the male mice." (PMID 36517890, 2022). "In CR, 52 AD-related target proteins were validated to bind with 25 active ingredients, including ACHE, APP, BCHE, BCL2, BAX, CASP3, and CASP7, and are implicated in cell apoptosis and vascular and nervous system diseases." (PMID 32802132, 2020). "The protective action in diseases of the nervous system has been tested in several experimental models, having the ability to interfere in AD, more specifically with phosphorylation of APP in cortical neurons." (PMID 33352989, 2020). "Amyloid-beta protein precursor (APP) levels are dysregulated in numerous neurological disorders that are comorbid with a seizure phenotype including fragile X syndrome (FXS)." (PMID 28018172, 2016). "Despite this physiological function of APP the protein contributes to neurological diseases like Alzheimer-, Huntington- and Parkinson or neuronal injury." (PMID 26426258, 2015). "Dysregulation of APP in blood of Parkinson's disease patients is interesting given its involvement in several neurological disorders." (PMID 24376773, 2013). "From this figure, we can easily conclude that aging genes FAS and APP are important to the linkage of immunological and neurological diseases." (PMID 19779549, 2009). "Elucidating how APP interactions contribute to normal neuronal functions offers insights into how APP may directly contribute to the pathogenesis of several neurological diseases." (PMID 37387352, 2023). "Proteins such as amyloid precursor protein (APP) vital in the pathological outcome of neurological disorders such as AD have been recently shown to be critically involved in the cholesterol turnover for neuronal activity, supporting the importance of cholesterol homeostasis in a wider context." (PMID 34744625, 2021). "By comparison, whether full-length APP or other non-Aβ APP processing products play a significant role in AD or contribute to other neurological disorders has received somewhat less consideration." (PMID 21527012, 2011).
neurological disorders (continued). "Therefore, targeting miRNAs which negatively regulate TNF signalling or APP expression directly may be used as strategy to prevent accumulation of this protein and subsequent neurological disease." (PMID 34572074, 2021). "In this work, we also found APP/PS1 mice displayed a declined level of acylcarnitine, which was not merely a cofactor in β-oxidation, but also had beneficial effects in the treatment of neurological diseases." (PMID 36618950, 2022). "Although most of the genes in the copy number alterations regions were related to the amyloid precursor protein (APP) molecular pathway, whether Pb is involved in neurological disease needs further elucidation, particularly in AD." (PMID 34335276, 2021). "On the other side, cotreatment with WSLE and WSLE NE revealed a signification downregulation of APP, GFAP, vimentin, TGF-β, Smad2, and BAX target genes which coincided with previous studies which highlighted the neuroprotective effect of WSLE in a variety of neurological disorders." (PMID 38630361, 2024). "In this sense, blocking JIP1-JNK could be an alternative to treat neurological diseases because even though knockout of JIP-1 did not affect APP transport or Aβ production, it interacts with the APP intracellular domain." (PMID 33352989, 2020). "In addition we will discuss the potential that either enhancement of non-amyloidogenic processing of APP or upregulating the expression of APPsα by other means has for preventing or at least slowing the progression of AD as well as treating other neurological disorders." (PMID 28223920, 2017). "To test this hypothesis, we analysed the APPpT668 level using WB and the APP–TrkA interaction using IP in brain samples from control subjects without neurological diseases (CTR; n = 3), patients with AD (AD; n = 3) and subjects affected by other neurological diseases (OND; n = 3)." (PMID 27076121, 2016).
metabolic disorders (19 papers, 2014 to 2025). "Furthermore, Os-pep treatment (5 μg/g, i.p., on alternating days for 45 days) regulated the levels of various biochemical parameters associated with metabolic disorders and AD in the serum of both APP/PS1, HFD and Adipo−/− mice." (PMID 33849621, 2021). "Pathway analysis of differential fecal metabolites revealed a pyrimidine metabolism disorder in APP/PS1 mice." (PMID 35992591, 2022). "Evidence shows that APP is essential for maintaining a healthy glycemic regulation, and it has been observed that APP knockdown mice develop metabolic disorders." (PMID 35269827, 2022). "As previously observed, metabolic disease affected the kinetics of amyloid deposition in APP/PS1 mice." (PMID 31992349, 2020). "In conclusion, we demonstrate that the brain of APP/PS1 mice is vulnerable to metabolic disorders induced by NAFLD." (PMID 31130652, 2019). "Using the APP/PS1 mice, this study demonstrated that TMF significantly reduced Aβ deposition and NFT formation and alleviated neuroinflammation and metabolic disorders." (PMID 39997198, 2025). "Notably, central genes (APP, MBP, and APOE) in the network are implicated in neuro-pathological disorders and metabolic disease, but have not previously been assigned significance in brain metastasis." (PMID 25593989, 2014). "The amyloid precursor protein (APP), down regulated in the SS LCL is included in the TGFβ signaling WikiPathway, the Reelin signaling in neurons IPA canonical pathway, and IPA network 4 for hereditary disorder, metabolic disease, organismal injury and abnormalities." (PMID 33669496, 2021).
brain disease (18 papers, 2012 to 2024). "ADutch-type cerebral amyloid angiopathy (D-CAA) is a hereditary brain disorder caused by a point mutation in the amyloid precursor protein (APP) gene." (PMID 36733499, 2022). "Dutch-type cerebral amyloid angiopathy (D-CAA) is a rare hereditary brain disease caused by a point mutation in the amyloid precursor protein (APP) gene [NM_000484.3(APP):c.2077G > C]." (PMID 36733499, 2022). "Apolipoprotein E (ApoE), Presenilin-1 (PSEN1) and Presenilin-2 (PSEN2), amyloid precursor protein (APP) and the linked mutations are some of the strongest risk factors that were observed to be associated with the brain disorder, Alzheimer’s." (PMID 27756223, 2016). "As a control, normalizing DSCAM gene dosage did not change the increased level of amyloid precursor protein (APP) in Ts65Dn, which is encoded by another HSA21 gene that is important for brain disorders of DS." (PMID 37079499, 2023). "Because APP is also highly expressed in the brain, the simultaneous presence of BACE 1 and APP can explain the reason why AD is a brain disease." (PMID 36291553, 2022). "The role and molecular mechanisms of exosomes carrying proteins related to the brain diseases [amyloid precursor protein (APP), α-synuclein (α-syn), mHtt, PrPsc] have been emphatically explored." (PMID 34588957, 2021). "This included brain disease traits with expression in the nervous system (antisense to APP and two antisense lncRNAs to MAPT) as well as immune-related diseases and enrichment in immune cells (antisense to LRRK2 and C9orf72)." (PMID 30610612, 2019). "Beyond rare familial brain disorders, neural GM has been linked to sporadic Alzheimer's disease (AD) through both increased DCV and specific CNV amplification of the pathogenic gene, Amyloid Precursor Protein (APP)." (PMID 30027562, 2018). "With relevance to brain disease, SORLA acts as a sorting receptor for APP, moving internalized APP from endosomes retrogradely to the TGN to prevent its breakdown into amyloid-β peptides in early endosomes." (PMID 37842085, 2023).
cardiovascular disease (11 papers, 2014 to 2025). "Based on PICRUSt2 statistical analysis, OXT intervention significantly reduced the abundance of microbial taxa associated with cardiovascular diseases in the OXT+APP/PS1‐SI group compared to the NaCl+APP/PS1‐SI group (p < 0.05)." (PMID 40635450, 2025). "In summary, AD-causing genes including APP and PSEN1/2 are involved in the development of cardiovascular diseases, and their mechanisms need to be further investigated." (PMID 39571156, 2024). "APP and its processing products are the link between aging and cardiovascular disease, and possibly vice versa." (PMID 36289917, 2022).
neurodevelopmental disorder (8 papers, 2016 to 2025). A behavioral and cognitive disorder with onset during the developmental period that involves impaired or aberrant development of intellectual, motor, or social functions. "Together, initial findings suggest a role for APP metabolites as peripheral biomarkers in neurodevelopmental disorders, though further characterization of peripheral APP metabolites and their association with clinical features are needed in FXS." (PMID 31551722, 2019). "There are functional aspects of APP which make it interesting to look at in neurodevelopmental disorders: APP regulates synapse formation, neurite outgrowth and neuronal plasticity." (PMID 33483523, 2021). "APP metabolism has been studied in the context of a variety of neurodevelopmental disorders including idiopathic autism, Angelman Syndrome, and FXS." (PMID 31551722, 2019). "Our results regarding sAPP and Aβ peptides in FXS plasma and brain tissue, support some sort of APP-driven anabolic pathway for neurodevelopmental disorders." (PMID 27212113, 2016).
autosomal dominant disease (7 papers, 2007 to 2024). Autosomal dominant form of disease. "Extensive research has shown that early-onset AD (EOAD) is usually an autosomal dominant inherited disorder that represents about 1–2% of all cases and involves mutations in the gene’s amyloid precursor protein (APP), presenilin 1 (PSEN1), or PSEN2." (PMID 36142483, 2022). "One form of the disease is familial AD, a very rare pure autosomal dominant disease with early onset before 65 years, which is caused by mutations in amyloid precursor protein (APP), presenilin-1 (PS1) or presenilin-2 genes all connected to Aβ accumulation." (PMID 32646017, 2020). "This rare autosomal, dominant disease with early onset (<65 years) is caused by mutations in the genes encoding amyloid precursor protein (APP) and presenilin (PSEN1), both linked to amyloid-β metabolism." (PMID 26301243, 2015). "Familial AD is a rare autosomal dominant disease with early onset, caused by mutations in the amyloid precursor protein (APP) and presenilin (PSEN) genes, both of which are linked to amyloid β (Aβ) peptide metabolism." (PMID 18047736, 2007). "Mutations in the amyloid precursor protein (APP) and presenilin genes, both linked to aβ metabolism cause familial AD, a very rare autosomal dominant disease with early onset." (PMID 38915346, 2024).
vasculopathy (7 papers, 2012 to 2025). "Alexander Venus from the group of Marc Fatar, Mannheim, serially investigated APP 23 („Swedish mutation“) transgenic mice by in vivo high-field (9.4T) magnetic resonance imaging (MRI) to visualize amyloid plaques, microbleedings and vasculopathy." (PMID 23174128, 2012). "A role of APP and its cleavage product beta-amyloid in the pathogenesis of other types of vasculopathy of the CNS has been reported previously." (PMID 29922220, 2018). "Taken together, our results indicate perivascular Aβ deposits in HIP and APP/PS1/HIP rats are potentially linked to altered spontaneous contraction/relaxation of cerebrovascular SMCs caused by the development of amylin vasculopathy." (PMID 36596993, 2023). "Our findings revealed that protein levels of eNOS and mRNA levels of Nos1 were decreased in APP/PS1 mice, indicating possible vasculopathy in the hippocampal region." (PMID 41164084, 2025). "Discussion: Our study demonstrates that the vasculopathy of PDR and AD is likely to share a common signaling pathway, of which the APP-related pathway is a potential target." (PMID 38328307, 2023).
genetic diseases (5 papers, 2013 to 2025). "Autosomal-dominant Alzheimer disease (ADAD) is a genetic disorder caused bymutations in Amyloid Precursor Protein (APP) orPresenilin (PSEN) genes." (PMID 23224319, 2013).
heart disease (5 papers, 2022 to 2025). "Although APP and C4BPA are associated with heart disease, we showed that these recurrent FBI polymorphisms in the two genes were non-causative factors of CHD." (PMID 37684230, 2023). "Both APP and PSEN genes were found to be expressed in the heart, suggesting that the role of APP-related gamma secretase activity in heart disease may not be ruled out." (PMID 37176125, 2023).
adenocarcinoma (4 papers, 2009 to 2025). A common cancer characterized by the presence of malignant glandular cells. "We conditioned APP-over-expressing cells (7W cells) and its parental cell line CHO cells for 36 hrs, and harvested Aβ-rich 7W CM and control CHO CM, then applied them to 6 wells of adenocarcinoma MDA-MB231-L cells, respectively (top panel CHO CM, lower panel 7W CM)." (PMID 19480719, 2009).
bacterial infection (4 papers, 2013 to 2022). "There is a plethora of data showing that systemic bacterial infections induce APP gene expression, and this knowledge has long been exploited for diagnostic purposes, as serum APP levels can be used as prognostic markers." (PMID 34858876, 2021). "Interestingly, decreased APP expression has been associated with recurrent bacterial infections." (PMID 34858876, 2021).
kidney disease (4 papers, 2016 to 2023). "Studies showed that kidney disease patients expressed a higher level of amyloid precursor protein (APP), a key protein for protein-bound receptor sorting (SorLA)." (PMID 36835994, 2023). "The amyloid precursor protein (APP) expression level in kidney disease patients is higher." (PMID 32824404, 2020). "In addition, the expression level of APP in patients with kidney disease is higher, and a key protein, SorLA (sorting protein-related receptor), that regulates APP processing is simultaneously expressed in both kidney cells and neurons, and the gene’s polymorphism is related to late-onset AD." (PMID 30429775, 2018).
myopathy (4 papers, 2009 to 2023). A disease of the muscle in which the muscle fibers do not function properly. "APP/Aβ pathology in muscles is strongly associated with myopathy in neurodegenerative disorders, including AD and ALS." (PMID 37175515, 2023). "All markers were detectable in GNE myopathy and the highest mean values of expression were noted for the degeneration-/cell stress associated markers αB-crystallin (1.052), desmin (0.315), ubiquitin (0.263), and APP (0.0226)." (PMID 23496965, 2013). "Despite absence of a cellular immune response, mRNA-expression of several inflammatory markers is present in GNE myopathy and some of them significantly correlated with αB-crystallin on the one hand and with APP on the other." (PMID 23496965, 2013). "mRNA-expression of APP, NCAM, iNOS, TNF-α and TGF-β was higher in GNE myopathy compared to controls, yet this was not statistically significant." (PMID 23496965, 2013).
gastrointestinal tumors (3 papers, 2020 to 2024). "APP has been associated with cell adhesion, cell motility, and cell proliferation, and APP proteins are highly expressed in gastrointestinal tumors." (PMID 36834821, 2023). "APP proteins are expressed in gastrointestinal tumours and their members are transported to the cell membrane, where they act in cell–cell interaction, cell adhesion, and metastatic processes." (PMID 38391955, 2024).
central nervous system diseases (1 paper, 2013). "APP, a marker of disrupted axonal flow marker, is regarded as a key predictor of axonal injury in central nervous system diseases." (PMID 23437066, 2013).
chromosomal disorder (1 paper, 2010). Clinical conditions caused by an abnormal chromosome constitution in which there is extra or missing chromosome material (either a whole chromosome or a chromosome segment). "The proximal pathogenesis of both pathologies likely derives from the primary chromosomal disorder and associated APP gene-dosage imbalance." (PMID 20502642, 2010).
neuromuscular disease (1 paper, 2023). "Understanding APP’s pathophysiological functions in muscles and NMJ is likely to uncover insights not only into neuromuscular diseases but also AD." (PMID 37175515, 2023).
retinopathy (1 paper, 2022). "A bioinformatics analysis revealed promising MMP9 and APP/Aβ partners for further scrutiny, many of which are already linked with retinopathy." (PMID 36498929, 2022). "The high concentrations of APP-derived fragments in ocular fluids also presented an opportunity to evaluate their relationships with age and retinopathy." (PMID 36498929, 2022).
APP also shares sentences with these, for which no sentence is quoted: cognitive disorder (12 papers); Lewy body dementia (6); hepatocellular carcinoma (5); Neurofibrillary tangles (5); age-related macular degeneration (4); cardiac arrest (4); chronic periodontitis (4); late-onset Alzheimers disease (4); Creutzfeldt-Jakob disease (3); gout (3); neurotoxicity (3); respiratory infection (3); rheumatoid arthritis (3); transmissible spongiform encephalopathies (3); acute T-cell leukemia (2); alopecia (2); Cerebral atrophy (2); Cerebral Autosomal Dominant Arteriopathy with Subcortical Infarcts and Leukoencephalopathy (2); cervical cancer (2); deficiencies (2); developmental delay (2); early-onset Alzheimers disease (2); esophageal cancer (2); essential tremor (2); familial amyotrophic lateral sclerosis (2); HIV dementia (2); infectious disease (2); liver disease (2); macular degeneration (2); medulloblastoma (2).
A further 149 diseases each share a sentence with APP in 2 papers or fewer.